LINC01988 (long independently transcribed non-coding RNA 1988)
Synonyms: PAAN
Gene: Long non-coding RNA gene on chromosome 3 (44,424,111 to 44,429,531, forward strand). Ensembl gene ENSG00000283036.
Diseases named in the same sentence as LINC01988 in open-access papers:
LINC01988 is named in the same sentence as 2 diseases in open-access papers, as found by Europe PMC text mining. Sharing a sentence is not in itself a finding about the gene and the disease.
LINC01988 shares sentences with these, for which no sentence is quoted: infection (1 paper); influenza (1).